GJB2 (gap junction protein beta 2)
Diseases named in the same sentence as GJB2 in open-access papers (continued):
Sharing a sentence is not in itself a finding about the gene and the disease.
HIV-1 infection (1 paper, 2025). The type species of lentivirus and the etiologic agent of acquired immunodeficiency syndrome (AIDS). "We investigated the underlying molecular mechanism of GJB2 inhibition of HIV-1 infection, revealing that GJB2 interfered with HIV-1 virion attachment to target cells, thereby inhibiting HIV-1 infection." (PMID 40980890, 2025). "Next, we took advantage of MX2, a host restriction factor inhibiting HIV-1 core translocation into the nucleus, to explore the underlying molecular mechanism responsible for GJB2 inhibition of HIV-1 infection." (PMID 40980890, 2025). "Overall, our findings demonstrated that the extracellular Ca2+-binding domains were critical for the anti-HIV-1 activity of GJB2 and that GJB2 required Ca2+ to inhibit HIV-1 infection in target cells." (PMID 40980890, 2025). "Overall, our study provides insights into the ability of myeloid lineage cells to interfere with HIV-1 infection through GJB2 and partially answers the question of how IL-4 enhances infection by downregulating GJB2." (PMID 40980890, 2025). "Collectively, our findings suggested that GJB2 was a potential novel target for the treatment of HIV-1 infection." (PMID 40980890, 2025). "Here, we identified GJB2 as a novel antiviral factor by demonstrating that IL-4-mediated reduction in GJB2 levels enhanced HIV-1 infection in myeloid cells." (PMID 40980890, 2025). "MX2 and GJB2 consistently inhibited HIV-1 infection, and this was statistically significant for GJB2." (PMID 40980890, 2025). "Herein, we found that IL-4 enhanced HIV-1 infection in myeloid lineage macrophages by downregulating the novel antiviral factor gap junction protein beta 2 (GJB2) located on the cell membrane." (PMID 40980890, 2025). "We then examined the effect of wild-type and mutant GJB2 on HIV-1 infection, revealing that EC1 or EC2 deletion almost abrogated its antiviral activity." (PMID 40980890, 2025). "Collectively, these findings indicated that GJB2 depletion using shRNA impaired the IL-4-mediated enhancement of HIV-1 infection." (PMID 40980890, 2025). "IL-4 is a well-known promoter of HIV-1 infection in primary macrophages (18, –, 20) and reduces GJB2 expression in macrophages." (PMID 40980890, 2025). "Therefore, IL-4 enhanced HIV-1 infection in myeloid lineage macrophages by downregulating the antiviral factor GJB2." (PMID 40980890, 2025). "Conversely, IL-6-mediated enhancement of HIV-1 infection was unaffected by GJB2 depletion." (PMID 40980890, 2025). "This led us to question whether HIV-1 accessory proteins or HIV-2 Vpx might compromise this GJB2-mediated inhibition to rescue HIV-1 infection in target cells." (PMID 40980890, 2025). "Interestingly, GJB2 silencing abrogated the IL-4-mediated enhancement of HIV-1 infection." (PMID 40980890, 2025). "We then investigated whether IFNs stimulated GJB2 expression to restrict HIV-1 infection." (PMID 40980890, 2025). "Collectively, these findings indicate that GJB2 suppresses cell-to-cell HIV-1 transmission and thereby inhibits HIV-1 infection in target CD4+ T cells." (PMID 40980890, 2025). "Therefore, we investigated whether GJB2 downregulation enhanced HIV-1 infection." (PMID 40980890, 2025). "Because IL-4 downregulated GJB2 expression to enhance HIV-1 infection in macrophages, GJB2 may be a novel target for the treatment of HIV-1 infection." (PMID 40980890, 2025). "Our findings showed that GJB2 silencing impaired IL-4- but not IL-6-mediated enhancement of HIV-1 infection, suggesting that IL-4-mediated downregulation of GJB2 expression enhanced HIV-1 infection." (PMID 40980890, 2025). "In contrast, GJB2 expression was unaffected by both the presence and absence of cytokine IL-6, which was reported to promote HIV-1 infection in primary macrophages." (PMID 40980890, 2025). "In the absence of IL-4, GJB2 knockdown still promoted HIV-1 infection in macrophages (shCtrl vs shGJB2 without IL-4)." (PMID 40980890, 2025).
HIV-1 infection (continued). "Additionally, unlike IL-4, the IL-6-mediated enhancement of HIV-1 infection in macrophages was unrelated to GJB2." (PMID 40980890, 2025). "Therefore, GJB2 may interfere with HIV-1 virion attachment to the cell membrane, restricting HIV-1 infection of target cells." (PMID 40980890, 2025). "In the absence of GJB2 (in shGJB2), IL-4 (20 or 50 ng/mL) did not enhance HIV-1 infection." (PMID 40980890, 2025). "Therefore, IL-4 but not IL-6 downregulated GJB2 to promote HIV-1 infection in macrophages." (PMID 40980890, 2025).
ichthyosis vulgaris (1 paper, 2013). The most common form of ichthyosis. "Analysis of samples from families with ichthyosis vulgaris and concomitant modifying gene mutations (STS deficiency, GJB2 deficiency) permitted correlation of alterations in protein profile with more complex genetic constellations." (PMID 24130705, 2013).
kidney cancer (1 paper, 2022). Primary or metastatic malignant neoplasm involving the kidney. "Our study revealed GJB2 germline pathogenic mutations in KIRC and KIRP for the first time, providing new evidence for the pathogenicity of the gene in kidney cancers." (PMID 36451132, 2022).
lymphedema (1 paper, 2025). Excess fluid collection in tissues, causing swelling. "For example, loss of expression of GJB2, encoding Cx26, suppresses peripheral lymphangiogenesis and causes severe lymphedema in mouse models." (PMID 40766782, 2025).
metastatic melanoma (1 paper, 2019). A melanoma that has spread from its primary site to another anatomic site. "Cx26 (GJB2) protein was detected as a cytoplasmic and occasionally cell membrane signal in melanocytes, and in A2058 and HT199 metastatic melanoma cells." (PMID 30717194, 2019).
osteoarthritis (1 paper, 2025). A noninflammatory degenerative joint disease occurring chiefly in older persons, characterized by degeneration of the articular cartilage, hypertrophy of bone at the margins and changes in the synovial membrane. "GSEA using the MSigDB database demonstrated that the GJB2, PAQR5 and CLEC12A genes activate inflammatory-related signaling (NES > 0) and suppress the cholesterol homeostasis (NES < 0), revealing their role in the meniscal degradation process during osteoarthritis progression." (PMID 40724902, 2025).
pneumonia (1 paper, 2025). An acute, acute and chronic, or chronic inflammation focally or diffusely affecting the lung parenchyma, caused by an infection in one or both of the lungs (by bacteria, viruses, fungi, or mycoplasma.). "Similarly, high frequency of MEFV variants in Middle Easterners and Ashkenazi Jews have been proposed to protect against Yersinia pestis infections, CFTR and GJB2 variants against diarrhea, and CYP21A2 variants have been hypothesized to decrease mortality from pneumonia." (PMID 40162233, 2025).
renal tubular acidosis (1 paper, 2018). A group of genetic disorders of the kidney tubules characterized by the accumulation of metabolically produced acids with elevated plasma chloride, hyperchloremic metabolic acidosis. "In our cohort, the c.88A>G GJB2 variant was found in two siblings of Arab descent (patient ID 267 and 308) with bilateral EVA, renal tubular acidosis (RTA) and no sequence alterations on the other GJB2 allele." (PMID 29320412, 2018).
viral infections (1 paper, 2025). "Further elucidation of the interaction between GJB2 and other viruses may help develop therapeutic strategies targeting viral infections." (PMID 40980890, 2025).
tumor (75 papers, 2003 to 2026). "Remarkably, the expression levels of GJB2 correlate with tumor mutational burden, microsatellite instability, neoantigens, and immune cell infiltration within the TME." (PMID 39162005, 2024). "It is known that higher GJB2 expression levels in a subset of cancer-associated fibroblasts (CAFs) induce stromal tumor fibrosis, enhancing chemotherapy resistance in solid tumors." (PMID 39737401, 2024). "Numerous types of cancer have been linked with GJB2, which has been shown to promote tumor growth, EMT, and lymph node metastasis." (PMID 38342890, 2024). "Functional enrichment analysis revealed that GJB2, a gene implicated in tumor biology, plays a multifaceted role in various cancer types." (PMID 39162005, 2024). "ESTIMATE analysis and Tumor Immune Estimation Resource (TIMER) database were utilized to illustrate the association of GJB2 with immune infiltration and components of the tumor microenvironment." (PMID 37188183, 2023). "GJB2 expression levels cor related with tumor mutational burden, microsatellite instability, neoantigens, and tumor infiltration of immune cells in multiple cancers." (PMID 37427102, 2023). "An increase in Connexin 26 (encoded by Gjb2 gene) has also been found to be related to apoptosis of tumor cells (encoded by Gjb1 gene)." (PMID 35563241, 2022). "We found that GJB2 was associated with various clinical factors in CC, such as age, tumor size, and differentiation grade." (PMID 35936685, 2022). "In early-stage MF, we observed gene expression differences in cells of both the stroma and the immune system, with keratinocytes exhibiting increased interferon response and proliferation (STAT1, ICAM1, HLA-DRA, GJB2), while fibroblasts displayed tumour-associated programs (CXCL2, TNFAIP6, CEBPD)." (PMID 41888970, 2026). "GJB2 encodes a gap junction protein and is a putative tumor suppressor." (PMID 35734583, 2022). "GJB2 is an oncogene associated with tumor growth, EMT, and metastasis in multiple types of cancer." (PMID 35196203, 2022). "Indeed, among only 30 genes identified, methylation of GJB2 (encoding Cx26) was associated with tumour stage in LUAD (Kruskal-Wallis p-value = 0.0001923, Q value = 0.119)." (PMID 30845770, 2019). "However, the impact of the GJB2 V178M variant on tumor cell biology remains to be elucidated." (PMID 39737401, 2024). "We found that increased GJB2 expression was linked to SCC histological classification (p = 0.045) and TNM stage (p = 0.022), while GJB3 expression was linked to larger tumor size (p = 0.045) and increased lymph node metastasis (p = 0.012)." (PMID 38562019, 2024). "Since TNTs and filopodia facilitate tumor invasion, we examined the boundaries in GJB2 knockdown and control tumors to analyze invasiveness." (PMID 38177502, 2024). "The size of invading tumor colonies as well as sinuosity, a measure of tumor infiltration, were significantly reduced in tumors with GJB2 knockdown." (PMID 38177502, 2024). "To explore the changes of TME caused by GJB2 deficiency, we developed sh‐RNA targeting mouse GJB2 to knocking down mouse HCC line H22, and detected subcutaneous tumor samples from mice injected with sh‐NC and sh‐GJB2 by mass cytometry." (PMID 39162005, 2024). "The characteristic marker FGA of the liver was mainly expressed in hepatocyte, the main marker KRT7 of tumor cells was mainly expressed in malignant cells, and we were excited to find that GJB2 was mainly expressed in malignant cells." (PMID 39162005, 2024). "GJB2 was over‐expressed in 65.5% (72/110) of tumor tissues and 51.8% (57/110) of normal tissues, while GJB3 was over‐expressed in 61.8% (68/110) and 48.2% (53/110) of the tumor and normal tissues." (PMID 38562019, 2024).
tumor (continued). "Our findings indicated that CD79A, COL5A1, ERO1A, and GJB2 were significantly overexpressed in tumor tissues compared to normal tissues, while CD101 and CPA3 showed more active expression in normal lung tissues, aligning with our prior analysis." (PMID 39850883, 2024). "The differential expression of GJB2 in the tumor and adjacent normal tissues of various cancer types was analyzed using the TIMER, GEPIA, and Sangerbox databases." (PMID 37427102, 2023). "The relationship between GJB2 expression levels and the tumor immune infiltration status in pan-cancer was analyzed by estimating the immune scores, stromal scores, and the ESTIMATE scores." (PMID 37427102, 2023). "In conclusion, our study demonstrated that GJB2 played an important role in tumor progression and was a potential prognostic predictor." (PMID 37427102, 2023). "The GJB2 in the tumor condition was elevated meaningfully, indicating that the content of GJB2 was upregulated with the LUAD progressing (P < 0.001)." (PMID 37188183, 2023). "This implied that GJB2 expression levels were associated with TME, especially tumor infiltration of immune cells." (PMID 37427102, 2023). "Subsequently, the correlation of GJB2 with clinical characteristics in the TCGA-LUAD database implied that GJB2 expression was positively related to tumor size, node metastasis condition, and clinical stage." (PMID 37188183, 2023). "Increasing GJB2 expression, age distribution, gender, race, T stage, N stage, M stage, and tumor TNM stage showed asymmetric distribution in the TCGA database, while patients’ OS displayed a declining tendency." (PMID 37188183, 2023). "Our study showed that GJB2 was involved in tumor cell proliferation and migration mainly through regulation of cell communication by electrical coupling, ion transmembrane transport, and autocrine signaling." (PMID 37427102, 2023). "Our results demonstrated that GJB2 was involved in immunomodulation and tumor infiltration of immune cells in multiple cancers." (PMID 37427102, 2023). "In the future, there is a need to develop and test anti-tumor immunotherapeutic agents targeting GJB2." (PMID 37427102, 2023). "Our study demonstrated that GJB2 played a significant role in tumorigenesis and tumor immunity in multiple cancers." (PMID 37427102, 2023). "In other oncological aspects, GJB2 was also reported as an oncogene related to tumor growth and metastasis in colorectal cancer, esophageal cancer, and breast cancer." (PMID 37188183, 2023). "Our results showed that GJB2 was involved in the tumor infiltration of immune cells in multiple cancer types." (PMID 37427102, 2023). "GJB2 is considered an oncogene and is related to tumor growth, EMT, and lymph node metastasis in a variety of cancers." (PMID 36016609, 2022). "Using the Chi-squared test, GJB2 was significantly correlated with age (p = 0.015), histology (p < 0.001), tumor size (p = 0.048), FIGO stage (p = 0.023), and differentiation grade (p = 0.001)." (PMID 35936685, 2022). "In contrast to these studies, we found that GJB2 is underexpressed in tumours and DRG1 is overexpressed." (PMID 14612907, 2003). "In addition, GJB2 knockdown reshapes tumor immune microenvironment and Salvianolic acid B inhibits the activity of GJB2." (PMID 39162005, 2024). "Thus, GJB2 and SCN9A are downregulated in anatomical regions with fewer tumor cells, while GJB2 is upregulated in highly proliferative and motile regions of GBMs." (PMID 38177502, 2024). "We would like to try whether inhibition of GJB2 combined with anti‐PD1 can enhance the anti‐tumor effect in vivo." (PMID 39162005, 2024). "This suggested that GJB2 may be of great significance in guiding the clinical treatment of cancer patients belonging to different ages, genders, and tumor pathological stages." (PMID 37427102, 2023).
tumor (continued). "Therefore, GJB2 is a potential target for immunomodulation in tumor therapy that can impact tumor growth, proliferation, and progression." (PMID 37427102, 2023). "The impact of GJB2 on tumor immunity also varies depending on the tumor type." (PMID 37427102, 2023). "Furthermore, we analyzed the prognostic value of GJB2 in pan-cancers and the association of GJB2 with the clinical pathological stages, immune checkpoint (ICP) genes, tumor mutation burden (TMB), microsatellite instability (MSI), and neoantigens." (PMID 37427102, 2023). "This suggested that GJB2 played a critical role in the tumor microenvironment." (PMID 37427102, 2023). "Moreover, when the tumor progressed from T1 to T2, the GJB2 gene expression was also elevated clearly (P=0.001)." (PMID 37188183, 2023). "Also, increased in tumor N stage, the expression of GJB2 gene tended to rise and a significant difference was observed between N0 and N1(P=0.014), between N0 and N2 (P=0.016)." (PMID 37188183, 2023). "Overall, the results showed that GJB2 regulated immune infiltration in multiple tumor types." (PMID 37427102, 2023). "We then investigated the prognostic role of GJB2 and the underlying molecular mechanisms in different cancers by analyzing the correlations between GJB2 gene expression and the status of survival outcomes, GJB2 gene alterations, tumor immune infiltration, and related cellular pathways." (PMID 37427102, 2023). "Furthermore, the association of GJB2 expression with the immune checkpoint (ICP) genes, tumor mutational load (TMB), microsatellite instability (MSI), neoantigens, and tumor infiltration of immune cells was analyzed using via the Sangerbox database." (PMID 37427102, 2023). "Furthermore, tumor infiltration levels of neutrophils, macrophages and DCs showed significant positive correlation with the GJB2 expression levels in several tumors, especially CHOL, KICH, and COAD." (PMID 37427102, 2023). "GJB2 could participate in several tumor biological processes, including extracellular matrix remodeling and upregulation of multiple cancer-related active pathways." (PMID 37188183, 2023). "The result indicated that tumor size (HR, 5.104; 95% CI, 1.402–18.584; p = 0.013), lymphovascular invasion (HR, 5.957; 95% CI, 1.245–28.492; p = 0.025), and high GJB2 expression (HR, 2.566; 95% CI, 1.066–6.180; p = 0.036) were independent predictors for patient prognosis." (PMID 35936685, 2022). "Furthermore, there were two genes (FBXW7, RET) mutated exclusively in tumours and eight (BLM, GJB2, NOTCH2, NOTCH3, NTRK1, POLE, SOS1, TSC2) solely in metastases." (PMID 34572946, 2021). "Hence, we propose the hypothesis that the tumor-promoting effect of GJB2 may correlate with the function of intercellular communication." (PMID 37188183, 2023). "However, more recent studies also showed that the expression level of GJB2 in metastatic tumor lesions is significantly higher than that in the primary tumor, suggesting that GJB2 may promote tumor metastasis." (PMID 35734583, 2022). "We conducted immunohistochemical staining of NSCLC tissue samples, revealing significant increases in GJB2 and GJB3 levels in tumor tissue samples compared to the control tissues." (PMID 38562019, 2024). "In GBM, we focused on two IP genes, GJB2 and SCN9A, and demonstrated their roles in promoting GBM aggression using patient-derived tumor cells and xenograft models." (PMID 38177502, 2024). "In conclusion, GJB2 promotes HCC progression by activating glycolysis through cytoplasmic translocation and generating a suppressive tumor microenvironment." (PMID 39162005, 2024). "Protein expression in mouse subcutaneous tumor tissue also suggested that CD86 protein expression was increased and CD163 expression was decreased after GJB2 knockdown." (PMID 39162005, 2024).